FOXF1 (forkhead box F1)
Diseases named in the same sentence as FOXF1 in open-access papers (continued):
Sharing a sentence is not in itself a finding about the gene and the disease.
tumor (continued). "On the other hand, FOXF1 has also been shown to be involved in tumor progression." (PMID 34257615, 2021). "Furthermore, to examine the in vivo effect of FOXF1 on tumor growth, we injected highly expressing FOXF1 cell lines H441-FOXF1H and H1299-FOXF1H in the mice, which revealed significantly decreased tumor size compared to their parental counterpart." (PMID 32370197, 2020). "This study also showed that FOXF1, in addition to acting as a reprogramming stemness regulator, could serve as a putative tumor suppressor, leading to p21-regulated growth suppression in fused progeny." (PMID 32370197, 2020). "In addition, two other transcripts (serglycin and FOXF1 adjacent non-coding developmental regulatory RNA) were identically found to be downregulated in MDR cells of both tumor models (NSCLC and CML)." (PMID 31947507, 2020). "Based on these results, FENDRR and FOXF1 could be postulated to be as potential tumor suppressor genes." (PMID 32284793, 2020). "While FOXF1 expression in tumor samples ranged from 0,00007 to 0.207, with a median of 0.0059." (PMID 32284793, 2020). "FOXF1 and EPAS1 are both TFs that have been associated with tumor malignancy." (PMID 31106044, 2019). "Therefore we used cisplatin, a known DNA-damaging agent, to examine FA protein levels in FoxF1-expressing tumor cells in vivo." (PMID 26625197, 2016). "In addition, FANCM phosphorylation did not occur and FANCD2 mono-ubiquitination was significantly reduced in tumor cells transfected with FoxF1-specific siRNA (lanes 5, 8)." (PMID 26625197, 2016). "Consistent with this hypothesis, proteasome inhibitor MG132 increased FA protein levels in FoxF1-depleted tumor cells." (PMID 26625197, 2016). "Furthermore, FoxF1 knockdown increased the frequency of nuclear abnormalities in cultured tumor cells." (PMID 26625197, 2016). "Therefore, we examined the number of chromosomal aberrations in metaphase of FoxF1-depleted tumor cells exposed to DNA-damaging agent." (PMID 26625197, 2016). "rs1728400 lies close to the FOXF1 locus which is a putative tumour suppressor gene." (PMID 25526632, 2014). "Decreased tumor sizes in EEV-Fzd4-treated mice were associated with increased number of TECs expressing Fzd4 mRNA as demonstrated by RNAscope with probes specific to Fzd4, Foxf1, and Aplnr, the latter of which is a specific marker of general capillary cells in the lung." (PMID 38589650, 2024). "Since FoxF1 levels are increased in alveolar rabdomyosarcomas, the most aggressive type of human rabdomyosarcoma tumors, FoxF1 could be involved in DNA repair of tumor cells, mediating increased resistance of these aggressive tumors to chemotherapy." (PMID 26625197, 2016). "Key TFs such as FOXF1, ETS1, NF-κB, and SNAIL cooperate with oncogenic drivers like PAX3-FOXO1 and epigenetic regulators to promote tumor growth, block differentiation, and support metastasis." (PMID 40508013, 2025). "Mechanistic studies have demonstrated that FOXF1 and its paralog FOXF2 are crucial for RMS tumor growth." (PMID 40508013, 2025). "We further identified upregulated transcription factors in these specific fibroblast subpopulations through transcription factor analysis, such as FOXF1 (a tumor suppressor transcription factor) and FOXQ1 (a tumor-promoting transcription factor)." (PMID 39963672, 2025). "H3K4Ac marks are also present in the transcription regulators Forkhead Box F1 (FOXF1) and BMI1 Proto-Oncogene, Polycomb Ring Finger (BMI1), that promote tumor progression and stemness." (PMID 33803458, 2021). "In the present study, we observed that depletion of FoxF1 from various cell lines, including MFLM-91U, HeLa, HT1080 and LLC tumor cells, reduced steady-state levels of FA proteins but did not affect their mRNA levels." (PMID 26625197, 2016). "FoxF1 co-localizes with FANCD2 in DNA repair foci in cultured cells and tumor tissues obtained from cisplatin-treated mice." (PMID 26625197, 2016).
tumor (continued). "Next, we compared the tumor/normal expression ratios with the methylation measured by BSA (FOXB2 and FOXF1) or array (FOXD3)." (PMID 23324568, 2013). "For a subset of nine tumor-normal pairs, the expression of FOXB2, FOXD3, and FOXF1 was determined using real-time reverse-transcription PCR (RT-qPCR)." (PMID 23324568, 2013). "FOXF1 and FOXC2 are part of the forkhead gene family, which are transcription factors originally identified as potential tumor suppressor genes." (PMID 23074687, 2012). "The results showed a significantly reduced tumor volume in the H441-FOXF1H and H1299-FOXF1H group compared to control (H441-FOXF1L and H1299-FOXF1L), indicating that FOXF1 could inhibit tumorigenesis." (PMID 32370197, 2020). "FOXF1 and EPAS1 are TFs that have been demonstrated to participate in tumor progression." (PMID 31106044, 2019). "Downregulation of OGT in tumor cells leads to increased degradation of the oncogenic transcription factor Forkhead transcription factor (FoxM1) protein, a direct regulator of VEGFR-2 and FoxF1 expression in EC." (PMID 25149532, 2014). "However, the upregulated methylation levels of FOXC2, FOXF1, FOXF2, FOXM1, and FOXN3 indicated that an epigenetic mechanism was not the main reason for the elevated FOX expression in tumor tissues." (PMID 36622275, 2023).
infection (1 paper, 2018). The state of being infected such as from the introduction of a foreign agent such as serum, vaccine, antigenic substance or organism. "Up to 90% decrease in FOXF1 mRNA expression was achieved 48 h after infection leading to a strong reduction of FOXF1 protein." (PMID 29963552, 2018).
renal disease (1 paper, 2017). "In situ hybridization analyses in mouse embryos identified Foxf1 expression in the development of most VATER/VACTERL organ systems except the urinary tract, questioning the significance of mutations in FOXF1 for renal disease manifestations." (PMID 28797033, 2017). "With our finding that Foxf1 is expressed and functionally required in ureter development in the mouse, the gene is (back) on the list of candidates for forms of CAKUT with additional extra-renal disease manifestations in human newborns." (PMID 28797033, 2017).
respiratory disease (1 paper, 2023). "Initial testing for genetic causes of respiratory disease and PAH (including sequencing for FOXF1, SFTPB, SFTPC, ABCA3) was negative." (PMID 36878902, 2023).
FOXF1 also shares sentences with these, for which no sentence is quoted: fibrosis (3 papers); atherosclerosis (2); Barrett esophagus (2); basal cell carcinoma (2); gastrointestinal stromal tumor (2); hydrops (2); idiopathic pulmonary fibrosis (2); medulloblastoma (2); Tracheoesophageal fistula (2); ventricular septal defect (2); adenocarcinoma (1); adenoma (1); alopecia (1); anal stenosis (1); anemia (1); anorectal malformation (1); Atrioventricular canal defect (1); autism (1); Bamforth-Lazarus syndrome (1); Blepharophimosis (1); breast tumor (1); capillary malformation (1); cardiac anomaly (1); cervical cancer (1); chronic myelogenous leukemia (1); Cobalamin C deficiency (1); congenital heart malformation (1); duodenal atresia (1); dysplasia (1); Epicanthus inversus (1).
A further 38 diseases each share a sentence with FOXF1 in 1 paper.